PARP1 (poly(ADP-ribose) polymerase 1)
Diseases named in the same sentence as PARP1 in open-access papers (continued):
Sharing a sentence is not in itself a finding about the gene and the disease.
breast cancer (continued). "The use of poly ADP-ribose polymerase 1 (PARP1) has been very common in the treatment of breast cancer and ovarian cancer, and its role may be to prevent the repair of fatal single strand breaks and double strand breaks in some genetic backgrounds." (PMID 39520627, 2024). "CDK4/6i treatment led to PARP1 upregulation in breast cancer patients and cells." (PMID 38037159, 2023). "PARP1 plays a role in chromatin remodeling and regulation of gene transcription in breast cancer." (PMID 36869202, 2023). "In addition, upregulation of transcription factor YB-1 also occurred in CDK4/6i-resistant breast cancer, and YB-1 inhibition can regulate PARP1 expression." (PMID 38037159, 2023). "Moreover, PARP1 was found to be a prognostic biomarker for a poor clinical outcome in breast cancer patients, therefore PARP1 inhibitors were extensively studied as a promising class of anticancer agents." (PMID 37033447, 2023). "Recently, to target poly(ADP-ribose) polymerase 1 (PARP1), researchers used E3 ubiquitin ligase murine double minute 2 (MDM2) ligand nutlin-3 derivative and PARP1 ligand niraparib derivative as a PROTAC, resulting in PARP1 degradation and apoptosis of human breast cancer cells MDA-MB-231." (PMID 38213543, 2023). "Previous research has revealed the relationship of p-YB-1 and PARP1 in cell line experiments, but the expression and colocalization of p-YB-1/PARP1 in breast cancer tissues are unknown." (PMID 38037159, 2023). "Then, we sought to determine whether simultaneous targeting of the enzymatic activity of PRMT6 and PARP1 elicits synergetic effects against breast cancer tumorigenicity." (PMID 36941223, 2023). "Thus, in WTBRAF melanoma, c-Met mediates the activation of PARP-1 upon exposure to ionizing radiations in a similar way described for breast cancer and hepatocellular carcinoma under oxidative stress." (PMID 37215708, 2023). "We also found that CDK4/6i treatment led to PARP1 upregulation in breast cancer patients and cells." (PMID 38037159, 2023). "The results showed that tumor growth was more strongly inhibited following combined administration of PRMT6 and PARP1 inhibitors, compared with either monotreatment, indicating a potent synergetic antitumor effect of the inhibitor in breast cancer." (PMID 36941223, 2023). "Moreover, knockdown of PRMT6 and PARP1 significantly impeded breast cancer cell invasiveness, whereas constraining PER3 expression restored it to normal levels." (PMID 36941223, 2023). "Consistently, DDX21 could stimulate breast cancer cell proliferation through activation of PARP-1, rDNA transcription, ribosome biogenesis, and protein translation." (PMID 37072811, 2023). "CDK-1 and PARP-1 play crucial roles in breast cancer progression." (PMID 37762072, 2023). "Indeed, PARP1 inhibitors have been used successful in the clinic for treating ovarian and breast cancers." (PMID 36814782, 2023). "Moreover, PARP1 was a prognostic biomarker for poor clinical outcomes in breast cancer patients; therefore, PARP1 inhibitors were extensively studied as a promising class of anticancer agents." (PMID 36430577, 2022). "Poly (ADP-ribose) polymerase-1 (PARP-1) inhibitors (PARPi) leverage deficiencies associated with homologous repair that are conferred by tumor mutations in BRCA-related genes, and have proven efficacy in breast cancer." (PMID 35729608, 2022). "Indeed, PARP1 inhibitors are currently one of the most promising therapeutic agents for several cancers, especially breast cancer, and can selectively target tumor cells with BRCA1 or BRCA2 tumor suppressor gene mutations through synthetic lethality." (PMID 36266635, 2022). "In addition, the same natural product inhibited human breast cancer tumorigenesis by inducing cell death through the ROS-mediated RIP1/RIP3/PARP-1 pathways." (PMID 36235123, 2022).
breast cancer (continued). "Increased levels of PARP1 have also been observed in breast cancer, gastric cancer, ovarian cancer, pancreatic cancer, and liver cancer The dependence of prostate cancer on PARP1 activity was shown in the reduction of AR to PARP1 inhibition." (PMID 36533080, 2022). "Notably, other group has published the regulation of CCL2 expression by PARP1/pADPr in breast cancer cells and demonstrated the importance of PARP1 localization in promoter for CCL2 effective transcription." (PMID 35585513, 2022). "Re-positioning of PARP1 inhibitors for patients with breast cancers may be needed, especially for ER-positive breast cancers." (PMID 35151316, 2022). "Furthermore, PARP-1 functions are extended in a disease-specific manner; for example, in breast cancer and prostate cancer, PARP-1 binds to estrogen (ER) and progesterone receptor (PR)." (PMID 35158955, 2022). "Some studies suggest that depletion of PARG leads to PARPi resistance in BRCA2-deficient mouse mammary tumor models, which results in increased PAR levels even when PARP1 is largely or partially inhibited, thus counteracting PARP1 trapping and promoting PARPi resistance." (PMID 36533080, 2022). "Thus, the application of a PARP1 inhibitor with RT leads to greater inhibition in BRCA2− than BRCA2+ breast cancers." (PMID 35643812, 2022). "PARP1/2 dual inhibitors, as all PARPis in current use are, may facilitate a tumor-supportive microenvironment and result in the growth of breast cancer bone metastases." (PMID 33923319, 2021). "Additionally, PARP1 is overexpressed in a variety of cancers, including glioblastoma, prostate and breast cancers." (PMID 32789690, 2021). "Finally, Poly-ADP-ribose polymerase 1 (PARP1) was shown previously to be upregulated in breast cancer, acting as an independent biomarker for poor prognosis." (PMID 33662042, 2021). "In addition, in more advanced stages of breast cancer, high PARP-1 expression helped in predicting survival: it correlated with shorter DFS and OS and increase risk of recurrence." (PMID 33572586, 2021). "In addition, by querying a proteomic resource for breast cancer, we found a significant positive correlation between the eIF3e and PARP1 protein abundances in the triple-negative breast cancer group." (PMID 33868586, 2021). "In addition, we sought to compare the relative requirement of these genes when DNA fidelity is challenged by clinically relevant anticancer breast cancer drugs, including cisplatin and PARP1/2 inhibitors, that have different mechanisms of action." (PMID 34857765, 2021). "One of the most interesting aspects concerning the role of PARP-1 in tumor immunology was a report demonstrating upregulation of the immunosuppressive cancer cell ligand PD-L1 in breast cancer cells treated with the PARP inhibitors, olaparib, talazoparib, and rucaparib." (PMID 33923319, 2021). "However, our results contrast with data from breast cancer, in which lncRNA H19 overexpression promoted doxorubicin resistance by downregulating PARP1 expression." (PMID 34295821, 2021). "Moreover, PARP1 alterations were positively associated with high transcription levels of PARP1, which might partially be due to increased PARP1 copy numbers, as evidenced by our results, which is in agreement with results of studies performed on breast cancer and cervical cancer, respectively." (PMID 34531868, 2021). "Finally, we expanded the synthetic lethality study of ICMT and PARP1 inhibition to other breast cancer cells." (PMID 34610973, 2021).
breast cancer (continued). "Furthermore, ICMT inhibition substantially increases the sensitivity of breast cancer cells to PARP1 inhibitor treatment, offering a novel therapeutic approach in the treatment of this group of cancers." (PMID 34610973, 2021). "Our results suggested that apoptosis could be induced in breast cancer cells through inhibition of c-Met/PARP-1 kinases activities." (PMID 32201536, 2020). "As expression level of PARP1 protein was proved to predict prognosis and chemotherapy sensitivity in breast cancer patients, we assumed that rs1136410 genotypes might relate to prognosis of TNBC." (PMID 32355298, 2020). "In our study, we provide evidence that the mechanisms of PARP1 action outside of DNA repair could be considered for treatment options for breast cancer patients." (PMID 32455851, 2020). "Knockdown of H19 sensitized breast cancer cells to doxorubicin by promoting PARP1 upregulation." (PMID 32345117, 2020). "Our study provides evidence that the inhibition of PARP-1 might be a pharmacological possibility for treating ER+ breast cancers by targeting transcription." (PMID 32059481, 2020). "Furthermore, PARP-1 was significantly increased in chemosensitive breast cancer tissues and Doxorubicin- chemosensitive MCF-7 cell." (PMID 32345117, 2020). "We synthesized these molecules and performed in vitro study to confirm that ZINC20032678 was the most effective small molecule which could induce two breast cancer cell lines apoptosis through inhibition of c-Met/PARP-1 kinases activities." (PMID 32201536, 2020). "We now show that PARP1 might be functional in multiple ways to regulate chemokines like CCL2 in breast cancer as well." (PMID 32455851, 2020). "We found that talazoparib, a new and highly potent PARP1/2 inhibitor for breast cancer treatment originally, could repress the growth of liver tumour cells." (PMID 32243714, 2020). "Furthermore, it was revealed that H19 negatively regulated PARP1 expression in breast cancer cells following doxorubicin treatment." (PMID 32345117, 2020). "Furthermore, the co‐expression of KLF4 and PARP1 in breast cancer cell lines and breast cancer tissues was detected with accumulation of KLF4 PARylation." (PMID 33231937, 2020). "However, PARP1 mediated cellular processes in the context of breast cancer are not fully understood." (PMID 32455851, 2020). "In the present study, PARP-1 expression was significantly downregulated in breast cancer tissues." (PMID 32345117, 2020). "Subsequently, in vitro study was carried out to confirm that the small molecule named ZINC20032678 which could both targeting c-Met/PARP-1 and induced breast cancer cell apoptosis." (PMID 32201536, 2020). "In addition, the combined diagnosis of PARP1, XRCC4 and ERCC1 has great predictive value for the risk of breast cancer metastasis." (PMID 33184404, 2020). "Recent clinical data confirmed that the cytoplasmic PARP-1 expression in the needle core biopsies of breast cancer was low, and low PARP-1 expression was associated with no or poor response to chemotherapy." (PMID 32345117, 2020). "It is reported that PARP-1 is considered as a guardian angel against breast cancer." (PMID 32201536, 2020). "In addition, we detected the PARP1 mRNA levels in the adjacent normal tissues of above breast cancer tissues." (PMID 32345117, 2020). "In order to analyzing the correlation of the KLF4‐PARP1 axis with poor breast cancer prognosis, we have conducted additional immunohistochemistry measuring the expression levels of KLF4 and PARP1 based on an array of 117 human breast cancer tissue samples followed by Kaplan–Meier analysis." (PMID 33231937, 2020). "Similarly, HIMOXOL (methyl 3-hydroxyimino-11-oxoolean-12-en-28-oate) also induced the activation of poly-ADP-ribose polymerase (PARP)-1 in MDA-MB-231 breast cancer cells." (PMID 32998255, 2020).
breast cancer (continued). "Although the proteolytic enzyme caspase-3 (CASP3) could initiates apoptosis by cleaving and inactivating PARP1, it also could stimulate survived breast cancer cell growth by promoting PGE2 release." (PMID 33246450, 2020). "However, inhibition of PARP-1 expression induces increased sensitivity towards the cell death in breast cancer cells." (PMID 33158052, 2020). "Since olaparib, a potent PARP-1, PARP-2 and PARP-3 inhibitor, has shown remarkable efficacy in BRCA mutated breast cancer 65, 66, a phase I/II trial tested the combination of 300 mg of olaparib twice daily and eribulin (at standard dose and schedule) in TN advanced BC patients." (PMID 31762800, 2019). "To confirm the possible role of PARP1 in the regulation of SWI/SNF-dependent transcription, we first tested whether PARP1 occurrence in the genome of breast cancer cells was accompanied by BRG1." (PMID 31614656, 2019). "Loss of PARP1: Immunohistochemistry studies have shown widely variable PARP1 levels in patients with ovarian and breast cancer, irrespective of BRCA status, but association with outcomes has been mixed." (PMID 35582575, 2019). "Based on these premises, we aimed to discover whether PARP1 co-regulates BRG1–EP300-dependent transcription, and if PARP1 can be considered an active component of such multiprotein complexes in the studied breast cancer cell lines." (PMID 31614656, 2019). "Elevated levels of oxidative stress in tamoxifen resistant breast cancer have been previously reported, which we postulate may correlate with increased PARP1 expression and activity, implicating PARP1 as a therapeutic target to overcome tamoxifen resistance." (PMID 30621214, 2019). "Regulation of PARP1 by miR-222 has been studied in depth in ovarian cancer cells; however, whether miR-222 is sufficient to increase PARP1 activity in breast cancer is unknown." (PMID 30621214, 2019). "PARP1 is overexpressed in a variety of cancers, including glioblastoma, prostate and breast cancer." (PMID 31500199, 2019). "In this study, PARP1 was shown to be an active component of the transcription machinery that drives BRG1-EP300-dependent gene expression by the poly-ADP-ribosylation of EP300 in breast cancer cells." (PMID 31614656, 2019). "We hypothesized that PARP1 activity mediated tamoxifen resistance in ERα-positive breast cancer and that combining the antiestrogen tamoxifen with a PARP1 inhibitor (PARPi) would sensitize tamoxifen resistant cells to tamoxifen therapy." (PMID 30621214, 2019). "Indeed, several PARP1 inhibitors in clinical trials and approved by governmental agencies are not limited to familial breast cancers." (PMID 31291457, 2019). "PARP1 was initially studied in the context of DNA damage, leading to the development and FDA approval of the PARP inhibitor olaparib for the treatment of BRCA-deficient ovarian and metastatic breast cancers." (PMID 29976663, 2018). "Accumulating studies propose RBBP8, known to encode the endonuclease CtIP, as a novel susceptibility gene whose functional loss increases sensitivity towards PARP1 inhibition similar to BRCA1 inactivation as, for instance, recently demonstrated in a mice xenograft model of breast cancer." (PMID 29445424, 2018). "Thus, we investigated the impact of olaparib (a competitive PARP-1/2 inhibitor) on the growth of MCF-7 breast cancer cells exposed to the RPM and to 1g-conditions." (PMID 29343717, 2018). "Since PARP1 inhibition induces accumulation of DNA damage in BRCA1-deficient cells, we tested if inhibition of EZH2 enhances the effect of the PARP inhibitor olaparib in BRCA1-mutated and BRCA1-reconstituted MDA-MB-436 human breast carcinoma cells." (PMID 29535829, 2018). "In addition, the effects of shRNA-mediated knockdown of endogenous RNF144A on the protein and mRNA levels of PARP1 were also observed in human breast cancer MCF-7 cells (respectively)." (PMID 29212245, 2017). "MiR-124 was reported to regulate PARP1 expression in breast cancer cells." (PMID 29312562, 2017).
breast cancer (continued). "Our recent studies demonstrated that RNF144A is downregulated in breast cancer (manuscript in preparation), which may provide a molecular basis of why PARP1 is upregulated in breast cancer at the protein level." (PMID 29212245, 2017). "High PARP1 expression is an independent prognostic factor for breast cancer recurrence and death." (PMID 29312562, 2017). "Interestingly, PARP1 activity is indispensable for normal proliferation of mammary tumor cells, in which a gene encoding an HRR factor BRCA1 is mutated, because PARP1 inhibition blocks alternative DNA repair pathways including NHEJ5." (PMID 29158484, 2017). "PI3K and Parp-1 inhibitors has proven effective in treating Brca1-related breast cancer in vivo." (PMID 29254138, 2017). "Importantly, we found that endogenous RNF144A interacted with endogenous PARP1 in human breast epithelial HBL100 cells and human breast cancer BT474 cells by IP analysis using an anti-PARP1 antibody." (PMID 29212245, 2017). "In addition to showing PARP-1-mediated cellular uptake in in vitro assays, [18F]-BO was also shown in PET experiments to accumulate specifically in PARP-1 overexpressing MDA-MB-468 breast cancer xenografts in mice." (PMID 28058462, 2017). "Collectively, the expression of PARP1 might be considered as an independent prognostic factor for the patients of breast cancer." (PMID 29152079, 2017). "Multiple lines of evidence have documented that PARP1 is upregualted in breast cancer." (PMID 29212245, 2017). "Moreover, induced expression of RNF144A decreases PARP1 protein levels and renders breast cancer cells resistant to the clinical-grade PARP inhibitor olaparib." (PMID 29212245, 2017). "Nevertheless, surprisingly, PARP1 inhibition improves the therapeutic index of radiotherapy independent of breast cancer subtype or BRCA1 mutational status." (PMID 28978184, 2017). "PARP1 is highly expressed in one-third of breast cancer patients." (PMID 29312562, 2017). "Interestingly, another study demonstrated that HER2+ breast carcinoma was highly sensitive to PARP1 inhibitors, due to the suppressing effect of PARP1 inhibitors on NF-κB inflammatory signal." (PMID 28991194, 2017). "PARP1 inhibitors are used to treat breast cancer exhibiting deletion of BRCA1 or BRCA2." (PMID 25872931, 2015). "In addition, the expression of PARP1 was correlated with pathology grade of breast cancer (P < 0.05)." (PMID 25865228, 2015). "In addition, mRNA expression of PARP1 was associated with high medullary histological grade, tumor size, metastasis-free survival (MFS) and overall survival in patients with breast cancer, and is an independent prognostic factor for MFS." (PMID 25411894, 2015). "35.0% (35/100) breast cancer tissues were positive for PARP1 expression in the nuclei; 34% (34/100) breast cancer tissues were positive for BRCA1 expression in both the nuclei and cytoplasm, 33% (33/100) breast cancer tissues were positive for BRCA2 expression in both the nuclei and cytoplasm." (PMID 25865228, 2015). "As a consequence, given the multiplicity of genes affected, PARP1 could be a potential target for the pharmacological management of breast cancer." (PMID 24243533, 2014). "Notably, recent data, including our own, have demonstrated an adverse prognostic impact of PARP1 overexpression in breast cancer." (PMID 25144364, 2014). "PARP1 also has a role in breast cancer, mediated by its interaction with the PR." (PMID 24243533, 2014). "PARP1 was found to be expressed in both normal/benign breast tissue and breast cancer specimens." (PMID 24392019, 2013). "Genotype Frequencies of PARP1 Gene Polymorphism in Breast Cancer Cases HER positive and HER negative." (PMID 24392019, 2013). "Another PARP-1 inhibitor olaparib has potent antitumor activity in breast cancer cells." (PMID 24367566, 2013).